TNF (tumor necrosis factor)
Diseases named in the same sentence as TNF in open-access papers (continued):
Sharing a sentence is not in itself a finding about the gene and the disease.
sarcopenia (continued). "Here, we aimed to develop a sarcopenia model in advanced hSkMOs by inducing muscle atrophy and wasting through repeated tumour necrosis factor‐alpha (TNF‐α) exposure." (PMID 40810394, 2025). "Pro-inflammatory cytokines like TNF-α and IL-6, released by adipose tissue, impair muscle protein synthesis while enhancing lipogenesis, promoting both sarcopenia and fat accumulation." (PMID 40251227, 2025). "Treatments targeting TNF‐α in in vitro culture systems have been widely utilized in muscle atrophy and sarcopenia modelling studies." (PMID 40810394, 2025). "The increased expression levels of IL-6 are positively correlated with the occurrence of sarcopenia, as well as TNF-α." (PMID 40265008, 2025). "Compared to the normal population and SO, TNF-α is significantly positively correlated with sarcopenia (SMD = 0.40, 95% CI (0.09, 0.71), K = 14, N = 2563, I2 = 89.7%)." (PMID 40507924, 2025). "Testosterone helped mitigate muscle wasting within the TNF‐α‐induced sarcopenia model, offering insights into hormone‐based strategies for the prevention of age‐related muscle loss." (PMID 40810394, 2025). "First, this study is the first to identify the dual involvement of TNF and PI3K/Akt signaling pathways in mediating VOC-associated sarcopenia." (PMID 41171716, 2025). "Lower BMI, lower serum ALB, FGF19, TNF-α, and higher circulating GDF11 are associated with sarcopenia." (PMID 40969368, 2025). "In particular, previous studies have reported that tumor necrosis factor-alpha (TNF-α) and interleukin-6 (IL-6) are closely linked to sarcopenia." (PMID 40098209, 2025). "Administration of gamma‐aminobutyric acid effectively suppressed M1 macrophage activation in both the gastrocnemius muscle and spleen, reduced proinflammatory cytokines TNFα and IL‐6, and consequently alleviated sarcopenia." (PMID 41357670, 2025). "Elevated amounts of pro-inflammatory cytokines like interleukin-6 (IL-6) and tumor necrosis factor-α (TNF-α), as well as C-reactive protein (CRP), are linked to sarcopenia." (PMID 40649397, 2025). "Chronic systemic inflammation, characterized by elevated pro-inflammatory cytokines such as interleukin-6 (IL-6) and tumor necrosis factor-alpha (TNF-α), serves as a pivotal intermediary between sarcopenia and cardiovascular complications." (PMID 40142260, 2025). "Inflammation is a key contributor to sarcopenia, and proinflammatory cytokines such as TNF-α, IL-6, and IL-1 are frequently elevated in individuals with sarcopenia." (PMID 40589442, 2025). "Research on chronic low-grade inflammation in the elderly has demonstrated that inflammatory cytokines such as IL-6 and TNF-α are significantly elevated in sarcopenia patients." (PMID 39556533, 2024). "Elevated levels of IL-6, IL-1β, TNF-α, and C-reactive protein (CRP) have been implicated in the loss of muscle mass and strength in sarcopenia." (PMID 39101140, 2024). "Population data have indicated that IL-6 and tumor necrosis factor α levels are significantly increased in older adults with sarcopenia; the higher the levels of IL-6 and C-reactive protein, the greater the risk of muscle loss." (PMID 39390392, 2024). "Future research is supposed to pay attention to “TNF-α,” “insulin resistance,” “mitochondrial autophagy,” “signaling pathways,” and “mechanisms” as pivotal areas in the study of oxidative stress in sarcopenia." (PMID 39588187, 2024). "Inflammation in particular has been linked to the development of sarcopenia, with data showing that individuals with sarcopenia have higher levels of circulating TNF-α and interleukin (IL)-6." (PMID 38911683, 2024). "Frail elderly individuals exhibit elevated levels of tumor necrosis factor-α (TNF-α) in comparison to healthy young adults, and interleukin-6 (IL-6) is significantly associated with sarcopenia." (PMID 39026669, 2024). "The assessment of TNF-α levels in blood or muscle tissue holds promise for the early prediction and diagnosis of sarcopenia." (PMID 39588187, 2024).
sarcopenia (continued). "Recent investigations have initiated the exploration of TNF-α as a potential biomarker for sarcopenia." (PMID 39588187, 2024). "It has also been reported that older people with sarcopenia show significantly higher levels of circulating IL-6 and TNF-α and that high levels of IL-6 and CRP increase the risk of loss of muscle strength." (PMID 39203857, 2024). "Human studies have shown that soy isoflavones reduce TNF-α levels and induce anti-inflammatory effects, potentially offering pronounced benefits for patients with sarcopenia." (PMID 39339684, 2024). "Several studies revealed that sarcopenia risk increases with circulating cytokines, such as CRP, IL-10, growth differentiation factor-15, and TNF-α." (PMID 39345889, 2024). "Currently, this is the first work that analyses the levels of irisin and TNF-α together in sarcopenic patients with cancer, and it is interesting because the inflammation present in many types of cancer can promote the onset of sarcopenia." (PMID 38672282, 2024). "Peptidoglycan can stimulate mononuclear phagocytes and endothelial cells to release small inflammatory molecules such as TNF-α, interleukins, and interferons, promoting the development of sarcopenia." (PMID 40008206, 2024). "Currently, there is conflicting research regarding the correlation between TNF-α and sarcopenia, and further research is needed to clarify this relationship." (PMID 38760722, 2024). "The IC domains composite score was significantly associated with functional ability, perceived health, sarcopenia, and systemic inflammation biomarkers such GDF-15, IL-10, and IL-10/TNF-α ratio in pre-frail older adults." (PMID 38510450, 2024). "In detail, patients with PACS are exposed to high systemic levels of sarcopenic cytokines, namely IL-6 and TNFα, which reduce the number and functionality of mitochondria in skeletal muscle cells, inducing sarcopenia." (PMID 39200115, 2024). "A meta-analysis based on 80 studies of sarcopenia and frailty showed that community-dwelling sarcopenic and frail individuals had higher blood TNF-α levels compared to age-matched healthy individuals." (PMID 40008206, 2024). "It was found that patients with sarcopenia have increased pro-inflammatory cytokine levels (interleukin-6, tumor necrosis factor α (TNFα)), C-reactive protein, and decreased levels of anti-inflammatory cytokine interleukin-10." (PMID 38505257, 2024). "Recently we demonstrated that a 10-month physical intervention significantly reduced the symptoms of sarcopenia through the changes to the body composition and physical performance and via the improvement in TNFα-related apoptosis." (PMID 37465171, 2023). "Subgroup analysis based on age (< 60 years) revealed a significant reduction of serum TNF-α following whey protein consumption, while subgroup analysis accounting for sarcopenia and pre-frailty status also exhibited a significant reduction of serum IL-6." (PMID 35706399, 2023). "Previous studies have shown that pro-inflammatory biomarkers, including IL-6, IL-10, IL-8, IL-15, CRP, TNF-α, and GDF-15, are associated with skeletal muscle decline and sarcopenia." (PMID 38026977, 2023). "Firstly, it has been observed that patients with sarcopenia exhibit elevated levels of inflammatory cytokines such as TNF-α, IL-1β, and IL-6." (PMID 38032288, 2023). "Such analysis would also benefit from the evaluation of skeletal muscle pathology on functional changes as well, since TNF-Tg mice are known to develop sarcopenia." (PMID 36732826, 2023). "TNF-α, a proinflammatory cytokine whose levels are elevated in aged subjects, has been demonstrated to be involved in the progression of sarcopenia." (PMID 37299588, 2023). "TNF-α has been validated to participate in the pathogenesis of sarcopenia through its complex intracellular signals." (PMID 36823174, 2023).
sarcopenia (continued). "The study discovered that patients with sarcopenia exhibit elevated levels of TNF-α, IL-1β and IL-6." (PMID 38032288, 2023). "Chronic, low-grade inflammation plays a central role in the progression of inflammaging and sarcopenia by modulating pro-inflammatory cytokines (TNF-α, IL-1, and IL-6." (PMID 36901121, 2023). "The expression of MHC1 reduced with a time course after TNF-α + TAK1i stimulation, reaching the minimal expression as early as 24 h, suggesting that TNF-α induced sarcopenia through TNF Complex IIb in myotubes." (PMID 36823174, 2023). "Second, proinflammatory mediators such as tumor necrosis factor-α and interleukin-6 play a pivotal role in the development and progression of sarcopenia." (PMID 36776611, 2023). "An animal study using the sarcopenic mice model found that TNF-α contributed to sarcopenia by mediating pyroptosis, one type of programmed cell death, through activating the pathways of caspase-8 and caspase-3." (PMID 38032288, 2023). "The study found that, compared with those in non-sarcopenia patients, the serum levels of IL-6, IL-18, TNF-α, TNF-like weak inducing factor of apoptosis (TWEAK), and leptin were significantly increased in sarcopenia patients." (PMID 37584041, 2023). "Compared with the nonsarcopenia group, serum albumin levels were significantly lower (4.3 ± 0.3 vs. 4.4 ± 0.3, p = 0.015) and serum TNF-α levels were significantly higher (1.97 ± 0.77 vs. 1.61 ± 0.64, p = 0.008) in the sarcopenia group." (PMID 37015998, 2023). "For instance, research examining the relationship between older adults sarcopenia and inflammatory factors revealed that patients with sarcopenia had significantly increased circulating concentrations of IL-6 and TNFα." (PMID 38235492, 2023). "Serum IL-10 levels were reduced in patients with sarcopenia, and the sarcopenia severity correlated positively with IL-6 and TNF-α levels." (PMID 37962457, 2023). "The cytokine storm, with IL-6 and TNF-α, is the event that correlates the degree of inflammation to sarcopenia, creating a high potential for multiorgan damage, including in skeletal and cardiac tissue muscle." (PMID 36992190, 2023). "A notable discovery has been made regarding the reduction of TNF-α, IL-1β, and IL-6 levels following exercise and nutritional support in individuals diagnosed with sarcopenia." (PMID 38032288, 2023). "Elevated levels of pro- and anti-inflammatory factors, such as interleukin (IL)-6, tumor necrosis factor (TNF)-α, and heat shock protein 27 (HSP27), are associated with sarcopenia and frailty." (PMID 37297995, 2023). "Sarcopenia was more prevalent in boys (77% vs. 24%, p = 0.004), patients with the perianal disease (69% vs. 29%, p = 0.03), and children with sarcopenia were likely to receive anti-TNF (77% vs. 41%, p = 0.05)." (PMID 37686870, 2023). "The GEE analysis adjusted by age and gender revealed sarcopenia significantly elevated TNF-α (p=0.003), IL-1β (p=0.001) and IL-6 (p<0.001), whereas intervention led to a decrease in TNF-α (p=0.005) and IL-1β (p=0.017) and an increase in IL-15 (p=0.024)." (PMID 38032288, 2023). "Elevated C-reactive protein (CRP), IL-6, and TNF-alpha have shown the strongest correlation with sarcopenia and frailty, resulting in extreme muscle wasting due to the promotion of catabolic signals mediated through these proinflammatory cytokines." (PMID 36979712, 2023). "TNF-α is also validated to play a prominent role in sarcopenia through its complex signaling pathways including cell death signaling." (PMID 36823174, 2023). "The expression of MHC1 declined with the concentration of TNF-α in myotubes, indicating that TNF-α can successfully induce sarcopenia in vitro." (PMID 36823174, 2023). "Of these inflammatory factors, C-reactive protein (CPR), interleukin-6 (IL-6) and tumor necrosis factor-a (TNF-a) are critical for predicting the incidence of sarcopenia." (PMID 36895911, 2023).
sarcopenia (continued). "Increased TNF-α plasma levels were also observed in sarcopenic patients (≥60 years) linking inflammaging to sarcopenia." (PMID 38132107, 2023). "Skeletal muscle tissue produces myokines, such as interleukin (IL)-6, IL-15, tumor necrosis factor-α, and transforming growth factor-β, and altered myokine activity can induce immune senescence in sarcopenia." (PMID 37958368, 2023). "Noteworthy, serum levels of IL-6 and TNF-α were significantly higher in sarcopenic patients, suggesting the role of these cytokines as inflammatory predictors of sarcopenia." (PMID 37238956, 2023). "Here, we first established naturally aged mice with sarcopenia model and confirmed an inflammatory state represented by TNF-α in aged mice." (PMID 36823174, 2023). "Our study result was in line with the previous animal and clinical studies, highlighting sarcopenia to be a pro-inflammatory status leading to elevated TNF-α, IL-1β, and IL-6." (PMID 38032288, 2023). "The concept of body fat, inflammation and balance between IL-10 and TNF-α, cellular senescence, mitochondrial dysfunction and sarcopenia needs to be further elucidated in the MCR participants and the role as a mediator for progression to dementia." (PMID 37371414, 2023). "Taken together, our data indicated that GSDME-mediated pyroptosis contributes to TNF-α-induced sarcopenia." (PMID 36823174, 2023). "Adipose tissue is a significant source of proinflammatory cytokines, such as IL-1β and IL-6, both probably involved in the development of sarcopenia, and TNF-α." (PMID 37373124, 2023). "A growing body of literature highlights how pro-inflammatory cytokines, such as interleukin-6 (IL-6) and tumor necrosis factor-α (TNF-α), contribute to the process of protein homeostasis dysregulation and, consequently, to sarcopenia." (PMID 37173873, 2023). "In particular, high levels of IL-6 and TNF-α are directly correlated with sarcopenia and weakness in humans and mice." (PMID 35250869, 2022). "A positive association was found between the high level of IL-6, IL-17A, and TNF-α and the prevalence of sarcopenia for both men and women." (PMID 35237317, 2022). "Inflammatory cytokines, including pro-inflammatory and anti-inflammatory cytokines interleukin 6 (IL-6) and tumor necrosis factor alpha (TNF-α), have been repeatedly proved to be closely associated with sarcopenia in humans and animals." (PMID 36111339, 2022). "IL-6, TNFα, and CRP are also strongly upregulated in primary sarcopenia, suggesting a causal role of inflammageing in muscle loss." (PMID 35276842, 2022). "Previous studies have shown an association of increased cytokines (e.g., TNF- α, IL-6, hs-CRP) with sarcopenia and progression of NAFLD." (PMID 35162699, 2022). "Pro-inflammatory biomarkers of systemic inflammation (tumor necrosis factor (TNFα), Interleukin-6 (Ile-6), act synergistically in the development of sarcopenia, which activates the ubiquitin-proteasome system." (PMID 36364963, 2022). "The present study demonstrated that the concentration of TNF-α in the sarcopenia group was significantly higher than in the control group." (PMID 36160136, 2022). "TNF-α is involved in the pathogenesis of sarcopenia and promotes pathological osteoclastogenesis and bone resorption in collaboration with receptor activator of nuclear factor kappa-B ligand (RANKL)." (PMID 36325442, 2022). "Systemic chronic inflammation and increased inflammatory markers such as CRP, IL-6, and TNF-α are related to increased muscle mass degradation and appearance of sarcopenia in ND-CKD patients." (PMID 35463026, 2022). "Stress-induced activation of NF-κB leads to upregulation of different cytokines, including IL-6 and TNF-α, which play a crucial role in the pathogenesis of sarcopenia." (PMID 35276842, 2022). "So far, studies have reported that serum levels of proinflammatory cytokines, such as TNF-α and IL-6, were increased in elderly sarcopenia cases." (PMID 35237317, 2022).
sarcopenia (continued). "Various cytokines involved in the pathogenesis of sarcopenia have been identified in foreign studies and include TNF-α, IL-1, IL-2, IL-4, IL-6, IL-8, and IL-10." (PMID 36160136, 2022). "We found that the levels of inflammatory cytokines IL-6, IL-17A, and TNF-α were increased in sarcopenia patients, while the IL-10 level declined." (PMID 35237317, 2022). "Pro-inflammatory cytokines including interleukin-6 and tumor necrosis factor (TNF) promote systemic inflammation, which leads to sarcopenia." (PMID 36125609, 2022). "In addition, sarcopenia leads to mitochondrial DNA (mtDNA) mutations, increased release of reactive oxygen species (ROS), increased pro-inflammatory agents such as interleukin-6 (IL-6), and tumor necrosis factor-α (TNF-α), interleukin-1 (IL-1), as well as C-reactive protein (CRP)." (PMID 35250869, 2022). "Positive associations were present between the severity of sarcopenia and IL-6, IL-17A, and TNF-α levels, while there was an inverse correlation between the presence of sarcopenia and IL-10 level." (PMID 35237317, 2022). "The anti-inflammatory cytokines (such as IL-4, IL-10 and IL-15) can counteract the expression and activity of pro-inflammatory cytokines, especially IL-6 and TNF-α, to reduce muscle atrophy and delay sarcopenia." (PMID 36111339, 2022). "Lastly, participants with a TNF-α > 71.2 were five times more likely to have sarcopenia [(OR = 5.85), 95% CI: 1.07–32.08; p = 0.04]." (PMID 36291982, 2022). "With regards to IBD treatment, at the time of sarcopenia assessment, about one-third of patients were treated with anti-TNF-α." (PMID 36079718, 2022). "Even before the tumor diagnosis, it is possible that these mechanisms, especially the neoplastic, inflammatory, microenvironmental (TNF, IL-1, proteolysis-inducing factor), and physical inactivity, play a role in the pathogenesis of sarcopenia." (PMID 35057564, 2022). "Two recent meta-analyses have been conflicting regarding TNF-α and IL-6, but both conclude elevated CRP is associated with sarcopenia." (PMID 36465176, 2022). "The present study investigated the relationship between the plasma pro-inflammatory factors TNF-α and IL-6 and the anti-inflammatory factors IL-4 and IL-10 in the elderly population and sarcopenia." (PMID 36160136, 2022). "Sub-acute inflammation manifested by small but significant increases in levels of inflammatory biomarkers (e.g., IL-6 and TNF-α) has been reported with aging and sarcopenia." (PMID 35334853, 2022). "Our study performed a cross-sectional analysis of serum concentrations of IL-6, IL-10, IL-17A, and TNF-α in the context of sarcopenia in elderly individuals." (PMID 35237317, 2022). "More specifically, a variety of cytokines, including tumor necrosis factor (TNF)-α, interleukin (IL)-1, IL-2, IL-4, IL-6, IL-8, and IL-10 play a role in the development of sarcopenia." (PMID 36160136, 2022). "Several studies have demonstrated that tumor-derived inflammatory cytokines, including tumor necrosis factor-alpha, interleukin (IL)-1-beta, and IL-6, are involved in the pathogenesis of sarcopenia in patients with malignancy." (PMID 35566740, 2022). "In contrast, combined exercise in people with sarcopenia increase thigh cross-sectional area and IL-10 and decreased TNF-α." (PMID 35250869, 2022). "Of note, aged mice with genetic TNF-α ablation exhibited reduced sarcopenia and better satellite cell activation." (PMID 36147742, 2022). "The predictive efficacy of the serum resistin level (AUC: 0.828) for sarcopenia was superior to that of the serum TNF-α level (AUC: 0.621)." (PMID 35903456, 2022). "Probably, TNF‐α and catalase are markers of an early inflammatory reaction that is impaired in subjects with sarcopenia." (PMID 33566325, 2021). "These functional changes contributed to the development of sarcopenia through anabolic resistance, chronic inflammation with elevated IL-6 and TNF-α, altered mitochondrial function, as well as oxidative stress." (PMID 33807573, 2021).